GOT2 (glutamic-oxaloacetic transaminase 2)
Diseases named in the same sentence as GOT2 in open-access papers (continued):
Sharing a sentence is not in itself a finding about the gene and the disease.
breast carcinoma (continued). "Importantly, we found that GOT2 can serve as an independent prognostic factor for overall survival and disease‐free survival of patients with breast cancer, especially triple‐negative breast cancer." (PMID 30714292, 2019). "Therefore, we proposed that GOT2 overexpression might be coupled with activation of histidine degradation pathway and nucleotide synthesis pathways to decrease the cellular level of THF, thus sensitized breast cancer cells to MTX." (PMID 30714292, 2019).
hepatocellular carcinoma (11 papers, 2021 to 2025). A malignant tumor that arises from hepatocytes. "Low GOT2 expression is associated with poor prognosis in patients with hepatocellular carcinoma." (PMID 38025761, 2023). "For instance, GOT2 expression is inversely regulated in hepatocellular carcinoma (HCC) tissues, where its downregulation is associated with adverse prognostic outcomes in HCC patients." (PMID 38915066, 2024). "GOT2 can assume a tumor-suppressive role in certain oncogenic contexts, particularly in hepatocellular carcinoma." (PMID 38915066, 2024). "Together, our findings provide new insights into the role of GOT2 in influencing malignant phenotypes by regulating migration in hepatocellular carcinoma cells." (PMID 38025761, 2023). "By analyzing the relationship between prognosis and GOT2 mRNA expression levels in patients with hepatocellular carcinoma in the TCGA database, we found that patients with low GOT2 expression had a worse prognosis in the TCGA database." (PMID 38025761, 2023). "Our study preliminarily explored the relationship between GOT2 and the prognosis of patients with hepatocellular carcinoma and preliminarily explored its effect on the migration ability of hepatocellular carcinoma." (PMID 38025761, 2023). "In our study, the prognostic curve confirms that GOT2 plays an important role in predicting survival in patients with hepatocellular carcinoma." (PMID 38025761, 2023). "The wound healing assay was used to assess the effect of GOT2 on the migration of hepatocellular carcinoma cells (Huh7 and MHCC97H)." (PMID 38025761, 2023). "Our research reveals that GOT2 is negatively related to the survival of patients with hepatocellular carcinoma and GOT2 may contribute to tumor progression by inhibiting the ability of tumor cells to migrate." (PMID 38025761, 2023). "As metabolic reprogramming was considered as one of the hallmarks of HCC, more importantly, gluconeogenesis, an essential metabolic process for hepatocytes, was downregulated in hepatocellular carcinoma, suggesting that hsa_circ_0002130 might regulate gluconeogenesis via GOT2." (PMID 34094907, 2021). "Importantly, although hepatocellular carcinoma (HCC) similarly exhibits glutamine addiction, GOT2 is lowly expressed in HCC cells, which is related to advanced progression and poor prognosis." (PMID 40247913, 2025). "Knockdown of GOT2 significantly increased the migration capacity of the Huh7 and MHCC97H hepatocellular carcinoma lines." (PMID 38025761, 2023). "To further explore the biological significance of GOT2 in the progression of hepatocellular carcinoma, we first transfected siRNAs targeting GOT2 (siGOT2) or negative control siRNA (siNC) in HEK293 cells and verified their knockdown efficiency by RT-qPCR." (PMID 38025761, 2023). "created a novel Hepatocellular Carcinoma prediction model that integrates 7 GlnMgs, including SLC1A5, GAPDH, SLC38A1, SLC38A7, FTCD, MTHFS, and GOT2 might be utilized to predict prognosis in HCC." (PMID 37377916, 2023). "In hepatocellular carcinoma (HCC), METTL14 was identified to be involved in the malignant progression of HCC by regulating m6A downstream targets, including cysteine sulfinic acid decarboxylase (CSAD), glutamic- oxaloacetic transaminase 2 (GOT2), and suppressor of cytokine signaling 2 (SOCS2)." (PMID 35731272, 2023).
Hepatic steatosis (7 papers, 2011 to 2025). Steatosis is a term used to denote lipid accumulation within hepatocytes. "An in vivo study suggested that increased mAST among alcoholics is a consequence of the pharmacologic up-regulation of GOT2 gene expression by ethanol, which further mediates fatty acid uptake, resulting in alcoholic fatty liver." (PMID 38277453, 2024). "Our findings showing elimination of HFD-associated hepatic steatosis and reduction in triglyceride levels in NQO1-Tg livers are consistent with decreased GOT2 activity." (PMID 33298924, 2020).
pancreatic ductal adenocarcinoma (7 papers, 2018 to 2025). An infiltrating adenocarcinoma that arises from the epithelial cells of the pancreas. "The knockdown of GOT2 in pancreatic ductal adenocarcinoma resulted in an increased production of ROS, which led to the cyclin-dependent kinase inhibitor p27-dependent senescence." (PMID 37693904, 2023). "GOT2 is a key component of mutant KRAS (KRAS*)-mediated rewiring of glutamine metabolism in pancreatic ductal adenocarcinoma (PDA)." (PMID 35815941, 2022). "Glutamate-oxaloacetate transaminase 2 (GOT2) knockdown (KD) impairs in vitro pancreatic ductal adenocarcinoma (PDA) proliferation." (PMID 35815941, 2022). "Moreover, PPARδ was found to dramatically accelerate pancreatic ductal adenocarcinoma development by activating the PPARδ-CCL2/CCR2 axis or the GOT2-PPARδ axis to drive immunosuppression through suppressing T cell-mediated anti-tumor immunity." (PMID 37572185, 2023). "Previously, inhibition of glutamic oxaloacetic transaminase 2 (GOT2) has been shown to lead to elevated levels of reactive oxygen species (ROS) and cyclin‐dependent kinase inhibitor p27‐mediated cell senescence in human pancreatic ductal adenocarcinoma cells." (PMID 30108113, 2018). "Glutamate-oxaloacetate transaminase 2 (GOT2) is not required for in vivo growth of pancreatic ductal adenocarcinoma (PDA) xenografts." (PMID 35815941, 2022). "Glutamate-oxaloacetate transaminase 2 (GOT2) deletion does not impact on pancreatic ductal adenocarcinoma (PDA) tumorigenesis in an autochthonous model." (PMID 35815941, 2022).
viral infection (7 papers, 2017 to 2025). "For instance, LncRNA‐ACOD1 interacts with glutamic‐oxaloacetic transaminase (GOT2) and supports virus infection through modulating cellular metabolic networks." (PMID 35312140, 2022). "A special viral infection-induced lncRNA aconitate decarboxylase 1 (ACOD1) directly interacts with glutamic-oxaloacetic transaminase-2 (GOT2) to enhance its enzymatic activity and provide metabolites for viral replication." (PMID 32174794, 2020). "Promotes viral infection and replication by interacting with GOT2 and increasing its catalytic activity to produce key metabolites required for viral replication." (PMID 30072977, 2018). "Likewise, upregulation of MAS components, particularly the aminotransferases GOT1 and GOT2, has been observed during viral infections." (PMID 41299514, 2025). "Overexpression of GOT2 promoted viral infection in macrophages by upregulating lncrNA-ACOD1." (PMID 37127605, 2023). "In cases of virus infection, Siniperca chuatsi rhabdovirus (SCRV) and infectious spleen and kidney necrosis virus (ISKNV) have been shown to upregulate the expression of GOT1, GOT2, MDH1 and MDH2, thereby supplying substrates for asparagine biosynthesis and promoting virus replication." (PMID 41299514, 2025).
colorectal cancer (6 papers, 2004 to 2025). A primary or metastatic malignant neoplasm that affects the colon or rectum. "GOT2 was reported by Du et al32 that ectopic expression of GOT2 could attenuate the SOX12 knock‐down‐induced suppression of colorectal cancer progression." (PMID 32285560, 2020). "The genes in the reported colorectal cancer group include POLR1D, DGKB, SULT2B1 SMPD1 GOT2, MTHFD1L and ACADM." (PMID 32285560, 2020). "Clinical statistical analysis shows that the overexpression of SOX12 promotes the proliferation and metastasis of colorectal cancer (CRC) cells by activating a variety of glutamine-metabolising enzymes, including GLS1, mitochondrial aspartate aminotransferase (GOT2), and ASNS." (PMID 37829798, 2023).
prostate carcinoma (6 papers, 2020 to 2025). A carcinoma that arises from epithelial cells of the prostate gland. "They found the significant upregulation of several genes involved in the citric acid cycle (including the GOT2 gene, which encodes the mitochondrial form of AST) in prostate cancer cells with a Gleason score > 7 compared to other cell types." (PMID 37894274, 2023). "Through a global lysine succinylation analysis of prostate cancer cells treated with fish oil, a significant number of lysine succinylation sites have been identified and FO-dependent GOT2 succinylation status may have a potential to inhibit building block generation." (PMID 37684043, 2023). "Notably, enzymes governing polyamine biosynthesis, including glutamic oxaloacetic transaminase 2 (GOT2), aminoacylase-1 (ACY1), ODC, and SDS, exhibit overexpression in prostate cancer, while ornithine aminotransferase (OAT) demonstrates insufficient expression." (PMID 41179661, 2025).
glioblastoma (5 papers, 2018 to 2026). The most malignant astrocytic tumor (WHO grade IV). "Consistently, GOT2 depletion reduces the proportion of glioblastoma cells in the S phase of the cell cycle." (PMID 42129945, 2026). "Functional assays reveal that GOT2 knockdown significantly suppresses glioblastoma cell growth, indicating that GOT2-mediated glutaminolysis is critical for their proliferation." (PMID 42129945, 2026). "Conversely, GOT2 had markedly lower expression in CHOL (Cholangiocarcinoma), GBM (Glioblastoma), KIRC (Kidney renal clear cell carcinoma), LIHC (Liver hepatocellular carcinoma), PRAD (Prostate adenocarcinoma) and THCA (Thyroid carcinoma)." (PMID 35735610, 2022).
endothelial dysfunction (4 papers, 2018 to 2026). In vascular diseases, endothelial dysfunction is a systemic pathological state of the endothelium (the inner lining of blood vessels) and can be broadly defined as an imbalance between vasodilating and vasoconstricting substances produced by (or acting on) the endothelium. "In summary, inflammation-driven upregulation of GOT2 contributes to endothelial dysfunction and hypercoagulability, both of which are mitigated following stem cell therapy." (PMID 41602836, 2026).
glioma (4 papers, 2019 to 2026). A benign or malignant brain and spinal cord tumor that arises from glial cells (astrocytes, oligodendrocytes, ependymal cells). "Among glutaminolysis-related enzymes, glutamic-oxaloacetic transaminase 2 (GOT2) shows a strong positive correlation with glioma grade and poor patient prognosis." (PMID 42129945, 2026). "The authors examined how hypoxia-induced stabilization of HIF-1α affects the expression of GOT1 and GOT2 in G55 human glioma cells, which possess the VHL protein and lack constitutive HIF-1α activation." (PMID 39914740, 2025). "Silencing HIF-1α with siRNA in the G55 glioma cell line reversed this hypoxia-induced suppression of GOT1 and GOT2 expression." (PMID 39914740, 2025).
lymphoma (4 papers, 2018 to 2024). A malignant (clonal) proliferation of B- lymphocytes or T- lymphocytes which involves the lymph nodes, bone marrow and/or extranodal sites. "This implies that directly targeting GOT2 could be considered as an effective strategy for treating lymphomas associated with EBV B-cell transformation." (PMID 38659762, 2024). "Cooperative NF-κB/STAT (signal transducer and activator of transcription) signaling regulates metabolic reprogramming and aspartate transaminase (GOT2) gene expression in lymphoma cells." (PMID 33542926, 2021). "We therefore conclude that GOT2 is expressed aberrantly in a subset of lymphoma and is characteristic of BL and a subgroup of DLBCL." (PMID 29666362, 2018). "Furthermore, high aberrant GOT2 expression is prognostic in diffuse large B-cell lymphoma underscoring the current findings and importance of stromal factors in lymphoma biology." (PMID 29666362, 2018). "Lymphoma tissues of HL, DLBCL, and BL patients, in contrast, stained strongly for GOT2 thus supporting the GE data." (PMID 29666362, 2018). "Among all genes, lactate dehydrogenase genes (LDHA and LDHB) were observed to be the most highly expressed (among the entire transcriptome), followed by transaminase genes (GOT1, GOT2, GPT, and GPT2) with log2 median expression > 10, both in lymphoma patients and cell lines." (PMID 39518046, 2024). "Remembering that high aberrant GOT2 is prognostic in DLBCL, transaminase inhibition might also represent an attractive treatment target in lymphoma." (PMID 29666362, 2018). "Whether targeting GOT2 and glutaminolysis or inhibiting Jak/STAT and NF-κB signaling is more efficient in corresponding lymphoma subtypes needs to be investigated in prospective preclinical and clinical studies." (PMID 29666362, 2018).
B-cell lymphoma (3 papers, 2018 to 2022). "In addition, glutaminolysis-dependent syntheses of aspartate and its linked pyrimidine in B-cell lymphoma cells are upregulated as a result of the transactivation of aspartate aminotransferase 2 (GOT2) by NF-κB, thus supporting cell proliferation." (PMID 35883815, 2022). "In order to gain insight into the role of GOT2 in B-cell lymphoma, OCI-Ly3, L-428, and CA-46 cells were selected." (PMID 29666362, 2018). "Our analysis demonstrates an important role of glutaminolysis and, in particular, GOT2 in B-cells and subtypes of B-cell lymphoma." (PMID 29666362, 2018). "Here the authors show that microenvironmental factors induce metabolic rewiring of B-cell lymphoma through activation of STAT3 and NF-ΚB resulting in upregulation of the aminotransferase GOT2 and glutamine addiction." (PMID 29666362, 2018).
cholangiocarcinoma (3 papers, 2020 to 2022). A carcinoma that arises from the intrahepatic biliary tree (intrahepatic cholangiocarcinoma) or from the junction, or adjacent to the junction, of the right and left hepatic ducts (hilar cholangiocarcinoma). "Interestingly, the expression of GOT2 has an unfavorable prognostic value in cholangiocarcinoma." (PMID 32599841, 2020).
epilepsy (3 papers, 2021 to 2025). A brain disorder characterized by episodes of abnormally increased neuronal discharge resulting in transient episodes of sensory or motor neurological dysfunction, or psychic dysfunction. "Interestingly, mutations in GOT2 were associated with early-onset of encephalopathy and epilepsy, which are also hallmarks of MoCD and ISOD pathophysiology." (PMID 33271457, 2021).
esophageal cancer (3 papers, 2022 to 2024). A primary or metastatic malignant neoplasm involving the esophagus. "In the unstratified analysis, all variants except ALDH1B1 rs2228093 and GOT2 rs73550818 showed significant associations (P < 0.05/8 = 0.00625) with esophageal cancer risk." (PMID 38277453, 2024).
gastric cancer (3 papers, 2017 to 2025). A primary or metastatic malignant neoplasm involving the stomach. "Our study showed that GOT1 and GOT2 were decreased in trastuzumab resistant gastric cancer cells with GATA6 knockout, suggesting that GATA6 maintains basal expression of GOT1 and GOT2." (PMID 33173435, 2020).
heart failure (3 papers, 2019 to 2023). Inability of the heart to pump blood at an adequate rate to meet tissue metabolic requirements. "We speculated that the low GOT2 level contributed to the rapid occurrence of pathological cardiomyocyte hypertrophy, causing strong plasticity of right ventricular cardiomyocytes in the early postnatal period and heart failure in adulthood." (PMID 38053021, 2023).
liver cancer (3 papers, 2020 to 2025). An epithelial or non-epithelial malignant neoplasm that arises from the liver. "The results of IHC for 90 liver cancer cases showed that the low protein expression of F2, GOT2, and TRPV1 was significantly associated with lower 5-year survival in HCC patients (F2: p = 0.033, GOT2: p = 0.035, TRPV1: p = 0.046; K-M survival analyses)." (PMID 32547951, 2020). "In liver cancer, multiple different groups’ investigations showed that METTL14 inhibits EMT, invasion and metastasis of liver cancer cells by regulating m6A-modified target mRNAs such as EGFR/PI3K/AKT, DGCR8/primiR-126, USP48/SIRT6/glycolysis, CSAD, GOT2 and SOCS2." (PMID 40734692, 2025).
cardiac hypertrophy (2 papers, 2017 to 2023). "GOT2 may regulate physiological and pathological myocardial hypertrophy in rats." (PMID 38053021, 2023). "The results of cell experiments showed that hypoxia induced a decrease in GOT2 protein expression of rat myocardial cell line H9C2 and an increase in the myocardial cell surface, which was familiar with Ang II-induced GOT2 reduction in adult mice with cardiac hypertrophy." (PMID 38053021, 2023).
clear cell renal cell carcinoma (2 papers, 2022 to 2025). "In clear cell renal cell carcinoma (ccRCC), reduced GOT2 expression is directly associated with abnormally high methylation of its promoter region." (PMID 40842990, 2025). "Bioinformatic analyses also revealed broad GOT2 expression in immune and stromal compartments of clear cell renal cell carcinoma." (PMID 40842990, 2025). "We observed that GOT2 expression was highest in patients harboring the C5 subtype (immunologically quiet) and lowest in patients exhibiting the C2 subtype (IFN-gamma dominant), indicating that GOT2 can be used as a marker for immunophenotyping of patients with clear-cell renal cell carcinoma." (PMID 35735610, 2022).
colon cancer (2 papers, 2017 to 2018). "When SIRT1-Flag tagged expression plasmid was transfected into Human colon cancer HCT116 cell line, the acetylation levels of SMARCA5, MTA2, HMGA1, EGFR, CHD4 and GOT2 decreased as equal amounts of the proteins were immunoprecipitated." (PMID 28676654, 2017). "Furthermore, five of the seven glycolytic and PPP enzymes identified in our interactome analysis (GOT2, GPI, PGD, PSAT1, and TKT) were found to map to the “Metabolic reprogramming in colon cancer” pathway." (PMID 30108113, 2018).
cutaneous melanoma (2 papers, 2023 to 2024). A primary melanoma arising from atypical melanocytes in the skin. "A recent study suggests that cutaneous melanoma (CM) patients with heightened GOT2 expression exhibit diminished survival rates and reduced immune cell infiltration." (PMID 38915066, 2024).
liver disease (2 papers, 2021). "We found on PheWAS that genetic variants in/near the genes coding for ALT (GPT), AST (GOT1/GOT2), and ALP (ALPL) did not themselves associate with liver diseases or other diagnoses suggesting that the liver enzymes are likely not themselves pathogenic." (PMID 33547301, 2021).
lung adenocarcinoma (2 papers, 2022 to 2023). A carcinoma that arises from the lung and is characterized by the presence of malignant glandular epithelial cells. "Both MDH1/2 and GOT1/2 are highly expressed in the malate-aspartic acid shuttle pathway of lung adenocarcinoma, and the high expression of GOT2 may promote the occurrence and malignant progression of lung adenocarcinoma." (PMID 37065159, 2023).
lymphedema (2 papers, 2021 to 2024). Excess fluid collection in tissues, causing swelling. "An increased expression of regulators of adipogenesis, glutamic-oxaloacetic transaminase-2 (GOT2) and WISP2, has been identified in lymphedema-associated adipose tissue." (PMID 38612716, 2024).
neuroblastoma (2 papers, 2022 to 2025). Neuroblastoma (NB) is the most common solid, extracranial childhood tumor. "Markers of acute mitochondrial dysfunction, such as decreased levels of ATP and mitochondrial glutamate oxaloacetate transaminase (GOT2) in human neuroblastoma (SH-SY5Y) cells and cortical tissue from C57BL/6J mice, have been reported at 6 h post-bTBI at lower BOPs." (PMID 40178780, 2025). "Additionally, the AADAT and GOT2, the KAT’s enzymes that lead to a KYNA formation, presented a decreased expression among the different tumors compared to the brain cortex, except in the neuroblastoma group, in which the expression of AADAT is higher compared to the brain cortex." (PMID 36355137, 2022).